WTAP (WT1 associated protein)
Diseases named in the same sentence as WTAP in open-access papers (continued):
Sharing a sentence is not in itself a finding about the gene and the disease.
cancer (continued). "Various literature has confirmed that WTAP, which acts as a critical m6A methylase, profoundly contributes to various cancers' pathogeneses." (PMID 35733918, 2022). "In conclusion, the regulation of WTAP on cancer development deserves further exploration, and the specific molecular mechanism of WTAP action needs to be further elucidated in order to achieve its therapeutic potential in cancer and other diseases." (PMID 36171885, 2022). "Here, we describe the recent findings on the structural features of WTAP, the mechanisms by which WTAP regulates the biological functions, and the molecular mechanisms of its functions in various cancers." (PMID 36139062, 2022). "Furtherly, although WTAP expression was found to be correlated with immune cell infiltration and patient prognosis, a cause-effect relationship could not be established and it could not explain or prove the relationship between immune infiltration and cancer survival." (PMID 36171885, 2022). "In conclusion, many studies have revealed WTAP as a potential biomarker for predicting cancer progression, since it participates in alternative splicing, cell cycle regulation and methylation." (PMID 36207306, 2022). "WTAP acting as an oncogenic factor was related to cell proliferation, migration, cancer progression, and lymphatic metastasis of OCs." (PMID 36545327, 2022). "As critical components of the m6A system, both METTL3 and WTAP have been shown to play an important role in various types of cancers." (PMID 34809621, 2021). "In nasal-type natural killer/T-cell lymphoma (NKTCL), WTAP contributes to cancer progression and chemotherapy sensitivity by stabilizing DUSP6 mRNA in an m6A-dependent manner." (PMID 34315512, 2021). "A growing body of evidence suggests that WTAP plays crucial roles in the tumorigenesis and progression of a variety of malignant tumors." (PMID 33937023, 2021). "WTAP also acts as an oncogene for the development of malignant tumors and a target for immunotherapy of cancer patients." (PMID 32903675, 2020). "Recently, the mRNA methylation complex containing METTL3, METTL14, and WTAP has been the subject of intense study in human cancers." (PMID 33133142, 2020). "In GBM, the splicing factors PTB, hnRNP H and A2/B1, and WTAP have been shown to regulate several biological processes relevant to cancer development." (PMID 27287018, 2016). "High levels of WTAP expression have been observed in osteosarcoma, gastric cancer, and cholangiocarcinoma, while it is downregulated in bladder urothelial carcinoma in a pan-cancer research." (PMID 41301778, 2025). "Moreover, PD1 protein levels and WTAP mRNA levels in tissue-infiltrating CD8+ T cells were increased in the HCC group compared to the para-cancer group." (PMID 40568348, 2025). "Based on the multiple functions of WTAP, targeting WTAP may become a new perspective for cancer therapy." (PMID 37297015, 2023). "Recent studies have shown that abnormal expression of WTAP is closely related to various pathophysiological events in cancer, including the cell cycle, metabolic vulnerabilities, autophagy, immune response, ferroptosis, epithelial mesenchymal transition (EMT), and drug resistance." (PMID 37297015, 2023). "A better understanding of the role of WTAP in cancer may render it a reliable factor for early diagnosis and prognosis, as well as a key therapeutic target for cancer treatment." (PMID 37297015, 2023). "Additionally, RNA modification genes, such as RBMX, HNRNPC, ALKBH5, and WTAP, play a crucial role in cancer biology." (PMID 38055673, 2023). "The Aberrant expression of WTAP has been observed in various cancers, including HCC." (PMID 38148841, 2023). "In particular, WTAP contributes to aggressive features of malignant tumors." (PMID 35046505, 2022). "The involvement of WTAP in malignant tumors has been investigated." (PMID 36171885, 2022).
cancer (continued). "WT1-associated protein (WTAP) has an important “writer” role in m6A modification, and it is also a nuclear protein that colocalizes with splicing factors and plays a critical role in cell function and cancer progression." (PMID 35733918, 2022). "Wilms’ tumor 1-associated protein (WTAP) is a key component of the human methyltransferase N6-methyladenosine (m6A) complex and is implicated in the initiation and progression of various human cancers." (PMID 35143566, 2022). "These cases indicated that the role of WTAP as a methyltransferase is vital in cancer progression." (PMID 36207306, 2022). "In addition, the expression of WTAP was positively correlated with the expression of the cancer proliferation markers Ki-67 and proliferating cell nuclear antigen (PCNA) in the HCC samples." (PMID 33937023, 2021). "There is evidence that WTAP participates in tumorigenesis and cancer progression." (PMID 34312368, 2021). "It has been shown that WTAP is overexpressed in variety of cancers." (PMID 34809621, 2021). "Compared with the control group, expression levels of HNRNPC, YTHDF1, KIAA1429, RBM15, YTHDF2, and METTL3 in cancer group were significantly up-regulated (P < 0.05), while expression levels of FTO, ZC3H13, METTL14, YTHDC1, and WTAP in cancer group were significantly down-regulated (P < 0.05)." (PMID 33193582, 2020). "Moreover, accumulating evidence suggests that WTAP contributes to aggressive features of numerous cancers." (PMID 31438961, 2019). "In addition, the association between WTAP expression and prognosis varies across cancer types, suggesting that the function of WTAP in cancer may be multi-dimensional and complex." (PMID 36171885, 2022). "Moreover, multiple reports highlighted the essential role of WTAP in the progression of cancers." (PMID 36362388, 2022). "However, the role of WTAP in cancers remains to be determined." (PMID 36171885, 2022). "Currently, multiple m6A writers, including METTL3, METTL14, WTAP, and VIRMA, have been shown to play critical roles in HIF-1 signaling, primarily in cancer progression." (PMID 40102715, 2025). "CESC, BRCA, LUAD, and COAD cell lines express lower amounts of METTL3 and FTO transcripts compared to their healthy counterparts, while WTAP and ALKBH5 expressions differ by cancer type." (PMID 38665783, 2024). "To investigate if the crosstalk between MALAT1 and molecular components of the m6A function orchestrates gene expression in cancer cells, we evaluated the functional relationship between MALAT1 and WTAP mRNA." (PMID 38862471, 2024). "IGF2BP2, IGF2BP3, RBM15, WTAP, and YTHDC2 are positively correlated to the immune score in a few cancer types." (PMID 39457524, 2024). "An increasing number of studies have confirmed that m6A writers (METTL3, METTL14, KIAA1429, WTAP), erasers (FTO and ALKBH5) and readers (YTHDC1, YTHDC2, YTHDF1, YTHDF2 and HNRNPC) have distinct functions within different types of cancer cells." (PMID 35042525, 2022). "WTAP expression is regulated by METTL3, with its oncogenic function in some cancer types found to be related to its m6A methyltransferase complex function." (PMID 36733939, 2022). "Among them, there were 12 m6A regulatory genes, including IGF2BP1, with a significantly higher expression in LUAD tissues compared with para-carcinoma tissues, while FTO, METTL14, WTAP, and ZC3H13 showed a significantly lower expression." (PMID 36249006, 2022). "We observed that WTAP, METTL3 and METTL14 were significantly upregulated in cancer vs. normal tissues, with METTL3 showing the most significant deregulation." (PMID 34530916, 2021). "However, the expression of WTAP, YTHDC1 and FASN was increased in NAFLD/NASH/HCC samples, indicating m6A-dependent downregulation of AP-2α during the inflammation-cancer progression." (PMID 40180937, 2025).
cancer (continued). "In numerous cancers, there is a consistent observation of dysregulated expression of key enzymes involved in m6A modification, including "writers" (such as METTL3, METTL14, WTAP), "erasers" (like FTO, ALKBH5), and "readers" (including YTHDF1, YTHDF2, YTHDF3)." (PMID 38270643, 2024). "In contrast, ZC3H13, IGF2BP1, WTAP, FTO, and YTHDC2 were downregulated in ≥four cancer types." (PMID 35211628, 2022). "In addition, G3BP2, WTAP, PCIF1, HNRNPA2B1, EIF3A, and IGF2BP2 were modulated in ≥three cancer types in uncertain manners." (PMID 35211628, 2022). "Then, we focus on the role of WTAP in cancers either dependent or independent of METTL3-METTL14 methyltransferase and summarize the specific mechanisms of WTAP in tumorigenesis and development." (PMID 36207306, 2022). "m6A methylation requires multiple protein complexes in the cell to complete, including writers (METTL3, METTL14, and WTAP), erasers (ALKBH5), and readers, among which METTL3 is involved in cancer progression by regulating the expression of a variety of cancer-related genes." (PMID 36347844, 2022). "Besides that, HNRNPA2B1, YTHDC1, METTL14, WTAP, and ZC3H13 were downregulated in cancer tissues, whereas VIRMA had opposite alterations between these two databases." (PMID 33225598, 2021). "METTL3, METTL14 and WTAP are the main partners of “writers” belonging to m6A modulators, of which METTL3 is the primary catalytic subunit and has proved essential in promoting metastasis in several cancers." (PMID 33563300, 2021). "Some WTAP-related pathways have been proposed such as EGF signaling, the mTOR pathway or the WT1-TBL1 axis, while the involvement of WTAP as an m6A regulator in human cancers has not been explored previously." (PMID 31438961, 2019). "Moreover, WTAP can also down-regulate the expression of CAV-1, activate the nuclear factor kappa B (NF-κB) signaling pathway in EC cells, promote EC cell proliferation, migration, and invasion, and accelerate cancer progression." (PMID 41256854, 2025). "Studies have reported that both STAT3 and HIF1-α can transcriptionally upregulate the expression of WTAP in some cancer cells, but we found that LPS-induced upregulation of WTAP was not affected by SC144 treatment, which inhibited the activation of STAT3 signaling by binding to IL6ST." (PMID 39007267, 2024). "A large number of studies of m6A regulatory mechanisms have investigated classical m6A regulators, such as METTL3, METTL14, WTAP, METTL16, FTO, ALKBH5, YTH family proteins, and IGF2BPs; anti-cancer target drugs targeting METTL3 and FTO have been proven to be effective against cancer." (PMID 38970366, 2024). "In conclusion, akin to METTL3, METTL4, METTL16, WTAP, RBM15/15B, VIRMA, and ZC3H13, the potential influence of YTHDC1, YTHDC2, YTHDF, IGF2BPs, the HNRNP family, eIF3, FTO, and ALKBH3/5 on autophagy is intertwined with their roles in RNA metabolism, collectively regulating autophagy in cancer." (PMID 38148841, 2023). "However, their results showed that in the absence of METTL3, an upregulation of WTAP alone was insufficient to promote cancer cell proliferation." (PMID 34281602, 2021). "Although the regulatory subunits of the m6A writers WTAP, VIRMA, ZC3H13, and HAKAI have been reported to be associated with cancers, whether their functional roles in cancers are dependent on m6A modification is not reported." (PMID 32245947, 2020). "Furthermore, Kaplan-Meier, meta-analysis and univariate Cox assay showed that the expression of m6A members including METTL3, METTL14, WTAP and FTO but not their gene mutation and amplification, was tightly associated with cancer progression and poor survival." (PMID 30953473, 2019). "Furthermore, the localization of WTAP in nuclear speckles and the formation of a complex with METTL3 and METTL14 need to be further investigated, since this knowledge may be useful for understanding the role of m6A modification in cancer biology." (PMID 36207306, 2022).
cancer (continued). "We found that C5RN cultivation promoted the expression of WTAP protein without affecting its mRNA levels, whereas inhibition of ERK1/2 signaling by SCH772984 reduced WTAP protein expression in cancer cells." (PMID 34312368, 2021). "Interestingly, although WTAP, METTL3, and METTL14 are core components of the same m6A methyltransferase complex, they do not necessarily exert identical biological effects across cancers." (PMID 41301778, 2025).
infection (6 papers, 2020 to 2025). The state of being infected such as from the introduction of a foreign agent such as serum, vaccine, antigenic substance or organism. "In contrast, our model focuses on pathogen infection, specifically examining how H. pylori modulates WTAP activity through lactylation, thereby activating a distinct cell-autonomous pathway via the YTHDF1-GLUT3 axis." (PMID 41384837, 2025). "Transcriptome analyses showed that infection with influenza A virus upregulated the expression level of WTAP (two of six experiments) but downregulated METTL3, RBM15, and VIRMA (one of six experiments, each)." (PMID 34502037, 2021). "Over the course of infection, levels of the assayed writers (METTL3, METTL14, and WTAP) and readers (YTHDC1, YTHDF1, and YTHDF2) remain unchanged." (PMID 33243990, 2020). "However, METTL3, METTL14, WTAP, ALKBH5, and FTO were all present in both the nucleus and cytoplasm after infection." (PMID 34225491, 2021).
cardiovascular disease (2 papers, 2021 to 2022). "Since that time, m6A methylation has been extensively studied, and its functions, mechanisms, and effectors (e.g., METTL3, FTO, METTL14, WTAP, ALKBH5, and YTHDFs) in various diseases, including cardiovascular diseases, have rapidly been investigated." (PMID 34221238, 2021).
endocrine system tumors (1 paper, 2020). "In general, it can be considered that WTAP, METTL16 and IGF2BP3 play important roles in the development of endocrine system tumors, WTAP, METTL16 are protective genes, IGF2BP3 is danger genes." (PMID 33237039, 2020).
inflammation (1 paper, 2024). Aberrant reaction of the microcirculation characterized by movement of fluid and leukocytes from the blood into extravascular tissues. "To further confirm the expression of METTL14, WTAP, METTL3, FTO and ALKBH5 in NPC tissues, we utilized RT‐qPCR to detect their expression in 28 NPC tissues and 7 nasopharyngeal chronic inflammation tissues." (PMID 39021049, 2024).
WTAP also shares sentences with these, for which no sentence is quoted: clear cell renal cell carcinoma (3 papers); rheumatoid arthritis (3); lymphoma (2); sarcoma (2); stomach adenocarcinoma (2); uterine corpus endometrial carcinoma (2); Wilms tumor (2); acute respiratory distress syndrome (1); adenocarcinoma (1); aging (1); alopecia (1); ankylosing spondylitis (1); bladder urothelial carcinoma (1); brain arteriovenous malformation (1); breast invasive carcinoma (1); breast tumors (1); Cerebellar atrophy (1); Cerebral ischemia (1); chronic kidney disease (1); colon adenocarcinoma (1); COVID-19 (1); Crohn disease (1); esophageal adenocarcinoma (1); head and neck cancer (1); hematological malignancies (1); Hyperglycemia (1); idiopathic cardiomyopathy (1); Infertility (1); inflammatory bowel disease (1); interstitial lung disease (1).
A further 22 diseases each share a sentence with WTAP in 1 paper.